CXCR6 (C-X-C motif chemokine receptor 6)
Diseases named in the same sentence as CXCR6 in open-access papers (continued):
Sharing a sentence is not in itself a finding about the gene and the disease.
lung carcinoma (continued). "The CXCR6‒CXCL16 axis is involved in several pathological processes, and they are overexpressed in different types of cancer, such as prostate, breast, ovary, and lung cancer, as well as schwannomas, promoting invasion and metastasis." (PMID 33920834, 2021). "The CXCR6‒CXCL16 axis is involved in several pathological processes, and its overexpression has been detected in different types of cancer, such as prostate, breast, ovary, and lung cancer, along with schwannomas, in which it promotes invasion and metastasis." (PMID 33920834, 2021). "Thus, membrane CXCR6 and CXCR4 were coexpressed in three lung cancer cell lines despite of a slight difference in the positive expression proportion." (PMID 24897301, 2014). "Expression intensity of CXCL16/CXCR6 and CXCL12/CXCR4 protein in human lung cancer tissues." (PMID 24897301, 2014). "Specific brown-coloured staining for CXCR6 and CXCL16 in the cytoplasm and membrane could be clearly observed in the primary lung cancer cells, but the positive expression rate and staining intensity of CXCR6 was stronger than that of CXCL16." (PMID 24897301, 2014). "We found that ORFV NA1/11 infection enhanced CXCL16 expression and secretion in lung cancer cells and co-culture of T cells from WT mice, but not from CXCR6-/- mice, with ORFV NA1/11-infected lung cancer cells promoted the migration of CD8 T cells in a transwell experimental system." (PMID 35959371, 2022). "However, we found that co-culture of T cells from either WT or CXCR6-/- mice with ORFV NA1/11-infected lung cancer cells greatly affected CD4 T cell migration regardless of their sources." (PMID 35959371, 2022). "Thus, it is reasonable to speculate that lung cancer cells could regulate their own biological functions in a self-regulation manner through the coexpression of CXCL16 and CXCR6." (PMID 24897301, 2014). "However, exogenous CXCL16 and CM effectively promoted the in vitro invasiveness of lung cancer cell lines, and the induced invasive ability could be obviously blocked by CXCL16 neutralizing antibody or CXCR6 gene down-regulation." (PMID 24897301, 2014). "CD103+ TRM, both in tumor and non-tumor tissue, are marked by expression of PDCD1, ITGAE, CXCR6, and SPRY1 in lung cancer." (PMID 32471032, 2020). "However, no studies have examined the impact by CXCR6 and CXCL16 on lung cancer survival." (PMID 26021984, 2015).
atherosclerosis (14 papers, 2008 to 2024). A disease characterized by the build-up of fatty material and calcium deposition in the arterial wall resulting in partial or complete occlusion of the arterial lumen. "Previous studies have linked CXCL16 and its receptor CXCR6 to inflammation-associated cancers, renal fibrosis, and vascular inflammatory diseases, such as atherosclerosis." (PMID 22748184, 2012). "However, dysregulation of the CXCR6/CXCL16 axis has been implicated in inflammatory conditions such as atherosclerosis and rheumatoid arthritis." (PMID 25888629, 2015). "This reduction in atherosclerosis was attributed to a reduction of CXCR6+ T cells within the aortas." (PMID 33503867, 2021). "A controversial role of the CXCL16/CXCR6 axis was found in atherosclerosis, suggesting that there exists a complex molecular mechanism between CXCL16/CXCR6." (PMID 33637127, 2021). "First, patients with metabolic syndrome, who are also prone to atherosclerosis development, have increased numbers of circulating CXCR6+ cells." (PMID 29326688, 2017). "While in a soluble form, CXCL16 has been found to interact with its receptor, CXCR6, and thus functions as an attractant and adhesion molecule for CXCR6-expressing T cells, which contribute to the development of atherosclerosis." (PMID 28286356, 2017). "During the past two decades, the role of CXCL16 and its receptor CXCR6 in the development of myocardial diseases and atherosclerosis has been controversially discussed." (PMID 26499307, 2016). "In contrast, CXCR6, the exclusive CXCL16 receptor, has been described to promote atherosclerosis in a cell unspecific CXCR6 knockout model by enhancing T-cell homing and macrophage accumulation." (PMID 25152735, 2014). "CXCL16 and CXCR6 were recently observed to be related to various inflammatory diseases, such as glomerulonephritis, pulmonary diseases, atherosclerosis, coronary artery disease, rheumatoid arthritis and many inflammation-related cancers." (PMID 34539750, 2021). "Hence, CXCL16 as well as platelet CXCR6 act as potent peripheral blood mononuclear cell adhesion ligands to the atherosclerosis prone vessel wall and thus promote the progression of atherosclerosis." (PMID 33503867, 2021). "Therefore, chemokine CXLC16 und chemokine receptor CXCR6 are potent adhesion molecules in the atherosclerosis-prone vessel walls and thus may promote the progression of atherosclerosis." (PMID 35784287, 2022). "It has been suggested that CXCR6 is a reliable marker of IFNɣ producing effector CD4 T cells, which drive Th1-mediated diseases like atherosclerosis." (PMID 33503867, 2021). "In an ApoE−/− mouse model where CXCR6 was replaced with a green fluorescent protein CXCR6GFP/GFP, a decrease in atherosclerosis was observed when compared with ApoE−/− mice." (PMID 33503867, 2021). "Chemokine (C-X-C motif) ligand 16 (CXCL16), a membrane-bound chemokine, acts as a ligand for C-X-C chemokine receptor type 6 (CXCR6) and contributes to the progression of many chronic inflammatory diseases, including fibrosis, nonalcoholic fatty liver disease, atherosclerosis, and cancer." (PMID 38172124, 2024). "In addition, various immune-related genes have been examined in an atherosclerosis animal model, and genes such as CXCR6, CXCL10, CXCR3 and CXCL16/scavenger receptor have been shown to be involved in the progression of atherosclerosis in animal models." (PMID 18673543, 2008). "The overall lack of CXCR6 reduces atherosclerosis and T cell accumulation." (PMID 39399488, 2024).
gastric cancer (13 papers, 2020 to 2026). A primary or metastatic malignant neoplasm involving the stomach. "CXCR6 has been linked to poor prognosis in gastric cancer and facilitates metastasis via epithelial–mesenchymal transition, with H. pylori infection exacerbating this process by increasing gastric cancer risk up to six-fold." (PMID 40445003, 2025). "In our study, CXCR6 was identified as an immune-related, favorable gene for prognosis in gastric cancer." (PMID 32410620, 2020). "Future research could focus on developing inhibitors against CXCL16 or CXCR6 and evaluating their efficacy in gastric cancer treatment." (PMID 40452847, 2025). "However, blocking CXCR6 has demonstrated potential in reducing gastric cancer cell migration and invasion, suggesting its viability as a therapeutic target." (PMID 40445003, 2025). "Likewise, CXCR6 expression in gastric cancer HGC-27 cells is positively associated with the proliferation of cancer cells, as well as CXCL16 expression in osteosarcoma U2OS and SaOS2 cells, and CXCR6 in osteosarcoma MG-63 cells." (PMID 33800554, 2021). "PPI network analysis highlighted eight key hub genes (CD80, CCR9, CXCR3, CXCR5, CXCR6, CCR3, CCL20, and CXCL1), revealing their pivotal roles in gastric cancer and H. pylori infection." (PMID 40445003, 2025). "Evidence was accumulated that chemokines and their receptors had a strong relationship with poor clinical outcomes in different tumor progression, such as that CCR6 and CXCL16/CXCR6 were involved in regulation proliferation, metastasis, and EMT in ESCC and Gastric cancer tumorigenesis." (PMID 34943853, 2021).
glioblastoma (12 papers, 2017 to 2025). The most malignant astrocytic tumor (WHO grade IV). "In our model, F4/80+ macrophages were responsible for CXCR6 expression, which is similar to findings in patients with glioblastoma." (PMID 36717913, 2023). "Although all CD8+ glioblastoma T-cell subsets expressed modest levels of CXCR6, expression was only enriched within glioblastoma compared to blood for Tcm and Temra cells." (PMID 35464424, 2022). "Overall, CCR5 and CXCR4 show the most prominent expression on CD8+ T-cell subsets in glioblastoma tissues, with CCR2, CXCR3 and CXCR6 displaying subset-specific glioblastoma enrichment in Tcm, Tem, and Tcm and Temra populations respectively." (PMID 35464424, 2022). "Having identified that CCR2+, CCR5+, CXCR3+, CXCR4+, and CXCR6+ T-cell subsets were enriched in glioblastoma, we subsequently validated the expression of complementary chemokines in dissociated glioblastoma biopsies and patient-derived glioblastoma cell-lines." (PMID 35464424, 2022). "In glioblastomas, CXCR6 is restricted to a subset of proliferating cells that are Musashi+, Nanog+, Sox2+, and Oct4+." (PMID 35269652, 2022). "Our study is also the first to identify CXCR6+ T-cell subsets as being enriched in glioblastoma, as well as demonstrating CXCL16 expression in dissociated tumour biopsies and glioblastoma cell-lines." (PMID 35464424, 2022). "In Vitro polarized macrophages with M-CSF or GM-CSF have much higher CXCR6 expression than TAM in glioblastoma multiforme." (PMID 33800554, 2021). "CXCL16/CXCR6 signaling can also act directly on tumor cells to promote their proliferation, migration and invasion in both human glioblastoma cells in vitro as well as in a glioma mouse model." (PMID 34503065, 2021). "Subsequent analysis showed that CTLA-4 was tightly associated with CXCR3, CXCR6, CXCL12, and T cell immunoreceptor with Ig and ITIM domains (TIGIT) in patients with glioblastoma." (PMID 31911758, 2020). "For this, we used human glioblastoma cell lines and a melanoma cell line as in vitro models to show that stimulation with recombinant C-X-C chemokine receptor 6 (CXCR6) or CXCR6-containing membrane preparations induces intracellular (reverse) signaling." (PMID 28698473, 2017). "Subsequently, chemokine receptors and integrins were validated at the protein level to reveal enrichment of receptors CCR2, CCR5, CXCR3, CXCR4, CXCR6, CD49a, and CD49d in glioblastoma-infiltrating T-cell populations relative to T cells in matched patient peripheral blood." (PMID 35464424, 2022). "Representative histograms for CD4+ T-cell subsets illustrate the typical chemokine receptor expression patterns observed, and demonstrate that staining for CCR2, CCR5, CXCR3 and CXCR6 was robust in glioblastoma-infiltrating T-cell populations compared to matched blood naïve CD4+ T cells." (PMID 35464424, 2022). "Whether CXCR6 drives T-cell migration, retention or survival in glioblastoma remains an important question given its requirement in CAR T-cell and ICI therapy in other tumour models." (PMID 35464424, 2022). "Together, our flow cytometry analysis demonstrates that CCR5 and CXCR6 are expressed by large proportions of all glioblastoma-infiltrating CD4+ T-cell subsets, whereas CCR2 and CXCR3 enrichment was only observed in glioblastoma-infiltrating CD4+ Tcm and Tregs, and Tem and Tregs respectively." (PMID 35464424, 2022). "Additionally, our scRNA-seq dataset revealed FOXP3 expression in a small proportion of glioblastoma Tregs, and expression of ITGA1, ITGAE, and CXCR6 which are associated with a Trm signature." (PMID 35464424, 2022). "Also in glioblastoma multiforme, it has been shown that CXCR6 is expressed predominantly on the CSC." (PMID 33800554, 2021). "In glioblastomas, CXCR6 is expressed by a small subset of tumor cells with stem cell properties, so that direct cell contacts might enable reverse signaling via CXCL16." (PMID 28698473, 2017).
glioblastoma (continued). "CXCR6, a marker of Trm cells, was indeed expressed by a high proportion of both CD4+ and CD8+ Trm cells in glioblastoma." (PMID 35464424, 2022). "Additionally, glioblastoma cells secrete C-X-C motif chemokine ligand 16 (CXCL16), which influences both TAMs and tumor cells through its receptor C-X-C motif chemokine receptor 6 (CXCR6)." (PMID 40427130, 2025). "CXCR6, an established marker of CD69+CD103+ Trm cells, was expressed on CD4+ Trm cells as anticipated, but also enriched in all other CD4+ T-cell subsets in glioblastoma compared to blood." (PMID 35464424, 2022). "Within glioblastoma-infiltrating T cells, a large proportion of cells were positive for CXCR4 and the proportion of cells positive for chemokine receptors CCR4, CCR5, CCR6, CCR7, CXCR3, and CXCR6 ranged between 5-25%." (PMID 35464424, 2022). "Moreover, C-X-C motif chemokine ligand (CXCL) 16 (CXCL16) is secreted by glioblastoma cells, and by signaling through C-X-C motif chemokine receptor (CXCR) 6 (CXCR6) it polarizes TAMs towards the M2-like phenotype." (PMID 34503065, 2021). "Next, we investigated the migratory potential of LOX-CXCL16 cells in comparison to LOX-pcDNA (control) and LOX-ΔCXCL16 (C-terminally truncated) and of T98G glioblastoma cells in a scratch assay with or without stimulation with recombinant CXCR6." (PMID 28698473, 2017). "To investigate a putative reverse signaling mediated by transmembrane CXCL16, we used CXCL16-positive and CXCR6-negative glioblastoma cell lines." (PMID 28698473, 2017). "To investigate a putative reverse signaling of transmembrane CXCL16 upon binding of its known receptor CXCR6, for the first approach, we used different CXCL16-positive, CXCR6-negative glioblastoma cell lines and stimulated them with 25 ng/mL recombinant CXCR6 for 10 or 15 min." (PMID 28698473, 2017). "To investigate intracellular signaling of CXCL16 upon stimulation with CXCR6, initially, we used human glioblastoma cell lines (known to express transmembrane CXCL16, but not CXCR6) and applied CXCR6 in different forms." (PMID 28698473, 2017).
influenza infection (11 papers, 2015 to 2025). "Published studies have demonstrated pathogen-specific TRM cells exhibit increased expression of CXCR6, which maintains them in the liver following malaria infection, and in the lung after influenza infection." (PMID 36153630, 2022). "In the same influenza infection model, fully differentiated CXCR6+ TRMs in the interstitium replenished the airway compartment, not circulating TEMs." (PMID 33979626, 2021). "In a murine model, the generation of influenza-specific memory-like NK cells characterized by the expression of CXCR6 was reported." (PMID 32517137, 2020). "Briefly, memory NK cells localize to the liver due to expression of CXCR6 and mediate protective responses against secondary influenza infection in mice." (PMID 32974217, 2020). "However, it has been shown in both tuberculosis and influenza mouse models that CXCR6 deficiency does not affect the capacity of cells to migrate into the lung but is associated with an improved control of the infection." (PMID 34283810, 2021). "A recent study showed that lung epithelial cells express the ligand for CXCR6 (CXCL16), and that CXCR6-CXCL16 interaction drives CD8 T cell localization within the lungs after an influenza infection." (PMID 37662932, 2023). "CXCL16 expression in the lung is important in CXCR6+ T cell homing; this is responsible for the recruitment and maintenance of TRM cells in the airways following influenza infection in mice." (PMID 32974217, 2020). "In the absence of significant changes in other NK cell markers (CD45RO, NKp44, CXCR6, CD57, NKG2C, CCR7, CD62L and CD27), influenza vaccines induced memory NK cells with the distinct feature of intracellular NKp46 expression." (PMID 25781472, 2015). "Therefore, although CXCR6 contributes together with other chemokine receptors to the integrated T-lymphocyte response to M. tuberculosis and influenza infection, it is not essential for the control of these infections." (PMID 30899256, 2019). "Therefore, CXCR6 is highly expressed by lung memory T-lymphocytes, but is not required for the retention and function of CD4+ or CD8+ TRM following influenza infection." (PMID 30899256, 2019).
Arthritis (10 papers, 2014 to 2025). Inflammation of a joint. "CCR4, CCR6, CCR7, CCR9, CXCR5, and CXCR6 deficiency ameliorated arthritis in CIA mice by suppressing the migration of Th17 cells (CCR4), DC (CCR7), and CD11b+ splenocytes (CCR9)." (PMID 36860872, 2023). "Correspondingly, CXCR6 knockout mice develop attenuated angiogenesis associated with profound decreases in arthritis progression and inflammatory cell recruitment to arthritic joints in K/BxN serum-induced mice." (PMID 27071670, 2016). "Indeed, genetic CXCR6 deficiency is protective in mouse models of arthritis, and antibody-mediated blockade of CXCR6 or CXCL16 ameliorates disease in a mouse model of MS." (PMID 39087473, 2024). "Moreover, CXCL16 blockade or CXCR6 deficiency led to reduced features of arthritis and lower IL-17 production in experimental models." (PMID 38405187, 2024). "Th1 and Th17 polarization were impaired in collagen-immunized CXCR6−/− mice, resulting in decreased development of collagen-induced arthritis." (PMID 27471636, 2016). "Before use in the K/BxN serum transfer arthritis studies, the CXCR6−/− mice were backcrossed onto the C57BL/6 background for more than 10 generations, making the C57BL/6 mouse the natural control for these experiments." (PMID 24620998, 2014). "We showed that deletion of CXCR6 (the only known receptor for CXCL16) prevents arthritis development, severity and joint tissue vascularity in mice in response to K/BxN serum." (PMID 24620998, 2014). "We recently showed a correlation among CXCR6 expression, arthritis development and angiogenesis in mice using the K/BxN serum transfer model." (PMID 24620998, 2014). "CXCR6 KO mice showed resistance to K/BxN serum-induced arthritis and CIA model." (PMID 36860872, 2023). "Finally, using the K/BxN serum induced arthritis model, we found that EC CXCR6 correlated with Id1 expression by immunohistochemistry." (PMID 24620998, 2014). "In addition, CXCR6−/− arthritic mice have markedly reduced Id1 expression in the K/BxN serum transfer model of arthritis." (PMID 24620998, 2014). "As in arthritis-irAE, CXCR3 and CXCR6 were suggested to play a key role in recruiting T cells into colitis-irAE sites." (PMID 35413951, 2022). "Similar to rheumatoid arthritis, in arthritis-irAE, SF T cells highly expressed CXCR3 and CXCR6, and their matching ligands, CXCL9/10/11, and CXCL16 were mainly produced by myeloid cells." (PMID 35413951, 2022). "However, Day 12 CXCR6−/− mice had significantly reduced arthritis and vasculature (data not shown) and completely lacked EC staining for Id1, showing that Id1 and the CXCL16-CXCR6 ligand-receptor pathway are linked and work together to recruit EPCs from the BM to the synovium." (PMID 24620998, 2014).